CASP1 (caspase 1)
Diseases named in the same sentence as CASP1 in open-access papers (continued):
Sharing a sentence is not in itself a finding about the gene and the disease.
Stroke (continued). "These in vivo findings provided solid evidence that curcumin suppressed stroke-induced microglial pyroptosis and caspase-1 activation." (PMID 34630845, 2021). "Therapeutic effects of suppressing the main executors (Caspase-1 and−11) of post-stroke inflammasome activation was also explored." (PMID 33967935, 2021). "Conclusively, we showed that the receptors of NLRP3, NLRC4, and AIM2, the executors of Caspase-1 and−11 were the main contributors of-post stroke inflammasome activation, which participated in the production of IL-1β, IL-18, and GSDMD." (PMID 33967935, 2021). "We have found that Caspase-1 and−11 were the main executors of post-stroke inflammasomes, and inflammasomes were activated mainly in macrophages within stroke lesions." (PMID 33967935, 2021). "Western blot results showed that the expressions of both NLRP3 and cleaved caspase-1 were greatly increased after stroke." (PMID 34630845, 2021). "Compared with sham and normal groups, the NLRP3, NF-κB, and cleaved caspase 1 protein expression increased significantly in both stroke group and stroke+PBS group (∗∗∗P < 0.001)." (PMID 32908485, 2020). "Caspase-1 KO mice and mice expressing dominant-negative caspase-1 exhibit a reduction of brain damage relative to wild type after experimental stroke." (PMID 29458437, 2018). "We then isolated EV from the serum of 16 aged-matched donors and 16 stroke samples and analyzed the protein levels of caspase-1, ASC, IL-1β, and IL-18 in these isolated EV with the Simple Plex technology." (PMID 30233311, 2018). "The increase of caspase-1 expression has been described in neurons and astrocytes after thromboembolic stroke and observed later in microglia (24 h post-stroke)." (PMID 29458437, 2018). "Previous researches show that caspase-1 KO mice and transgenic mice expressing a dominant-negative caspase-1 construct are partially resistant to cerebral disease and stroke." (PMID 29458437, 2018). "The present study concludes that MCC950 shows appropriate in vivo efficacy to repress NLRP3/Caspase-1/IL-1 signaling enough to improve acute stroke outcomes in a MCAO model of stroke." (PMID 29654318, 2018). "In the permanent stroke model, the proteolytic activity of caspase-1 is increased 30 min after occlusion with a second wave of activation 12 h later." (PMID 29458437, 2018). "We have previously shown that the inflammasome, an arm of the innate immune response involved in the activation of caspase-1 and the pro-inflammatory cytokines interleukin (IL)-1β and IL-18, contributes to the pathology of stroke." (PMID 30233311, 2018). "Caspase-1 (i.e., Interleukin 1β converting enzyme) is known to play a key role in both inflammation and programmed cell death, particularly in stroke and neurodegenerative diseases." (PMID 26903786, 2016). "The highest scoring network in males at 3 h had convergent nodes on CREB, Caspase-1, and ERK1/2, all having been implicated in stroke." (PMID 25036109, 2014). "This caspase 1-dependent cell death, is inherently inflammatory, is triggered by various pathological stimuli, such as stroke, heart attack or cancer, and is crucial for controlling microbial infections." (PMID 25111876, 2014). "NLRP3 inflammasome can activate caspase-1 state to cleaved, which in turn exposes the N-terminal of GSDMD for pore formation in cell membrane and promotes secretions of IL-1β and IL-18, causing serious of outcomes in stroke." (PMID 40289983, 2025). "Therefore, the NF-κB/NLRP3/Caspase-1/GSDMD pathway is involved in cerebral ischemia-reperfusion damage after stroke." (PMID 39199474, 2024). "Furthermore, deregulated activation of caspase-2, caspase-3, and caspase-8 contributes to the exacerbation of liver disease injury, while caspase-1, caspase-3, and caspase-6 knockout protect against stroke." (PMID 39625520, 2024).
Stroke (continued). "Correspondingly, we found a significant increase in circulating cfDNA in plasma of patients with stroke, as well as a substantial increase in markers of inflammasome priming (pro-caspase-1 expression) and inflammasome activation (cleaved p20 isoform of caspase-1) in plaque material." (PMID 39112714, 2024). "Although genetic knockout of caspase-1, caspase-3, and caspase-6 provides neuroprotection against stroke, one may ask whether apoptosis plays a critical role in ischemic stroke." (PMID 39625520, 2024). "Also nitrosonisoldipine is an inhibitor of the Caspase family, which possesses good inhibitory effects on both Caspase-1 and Caspase-11 and can inhibit pyroptosis, and therefore can be a candidate for stroke treatment." (PMID 37165005, 2023). "The expression of NLRP3, ASC, and cleaved-caspase-1 significantly elevated at 6 h post-stroke (* p < 0.05, ** p < 0.01 vs. Sham group), while IPC treatment could partially reverse it (#p < 0.05 vs. pMCAO group)." (PMID 37371374, 2023). "Hence, in this review, we are concerned about the roles of caspase-1 activation and its associated mechanisms in stroke-induced BBB damage, aiming at providing insights into the significance of caspase-1 inhibition on stroke treatment in the near future." (PMID 35370546, 2022). "However, the mechanisms about caspase-1 inhibition on stroke-induced BBB damage remain ill-defined yet." (PMID 35370546, 2022). "Considering the caspase-1 activation to be a hub, which is converged by various triggering pathways to promote diverse programmed death patterns, namely, pyroptosis and apoptosis, it should be notably indispensable and potent during a stroke." (PMID 35370546, 2022). "Therefore, we will first review the priming and triggering processes of caspase-1 during a stroke in this part." (PMID 35370546, 2022). "An increasing number of evidence has shown that Z-VAD-FMK or AC-YVAD-CMK, caspase-1 inhibitors, could reduce inflammasome activation-mediated inflammatory response and neuronal cell death after stroke." (PMID 35401398, 2022). "Whether superimposed effects exist among caspase-1 and other risk factors on BBB disruption in stroke, such as hypertension, hyperlipidemia, as well as aging, deserves further research." (PMID 35370546, 2022). "Therefore, inhibitors of Caspase-1 or Caspase-11 were injected intravenously and at 1 h, a time point prior to the pre-prime of inflammasome and the infiltration of myeloid cells into stroke lesion." (PMID 33967935, 2021). "Increased caspase 1 and IL-1β in phenotypically modified VSMCs was detected in the aortic roots of VSMCs lineage tracing mice fed high cholesterol diet and in human atherosclerotic plaques from carotid artery disease patients who experienced a stroke." (PMID 35008765, 2021). "Since Caspase-1 and −11 keep the gate of post-stroke inflammasome activation, targeting the enzymes for inflammasome inhibition may be more efficient than the receptors." (PMID 33967935, 2021). "Furthermore, curcumin significantly reduced the number of gasdermin D+ (GSDMD+) Iba1+ and caspase-1+Iba1+ microglia/macrophage 21 days after stroke." (PMID 34630845, 2021). "NLRP3 inflammatory response is associated with microglia activation which maybe contributed to the neuron recovery after stroke though NF-κB and caspase 1 activation." (PMID 32908485, 2020). "Other studies have demonstrated the role of caspase-1 after stroke using transgenic mice." (PMID 29458437, 2018). "Moreover, intracerebroventricular administration of caspase-1 inhibitors provides protective effects in experimental stroke models." (PMID 29458437, 2018). "Sensing several stroke-induced stimuli, the cytosolic pattern recognition receptor NLRP3 recruits the adapter protein the apoptosis-associated speck-like (ASC) pro-caspase-1 leading to caspase-1 production and subsequent interlukin-1 β (IL-1β) maturation and release." (PMID 29654318, 2018).
Stroke (continued). "Nevertheless, as we detected less pro-caspase 1 levels in MCC950 stroke animals, the eventual modulation of inflammatory cytokines arguably may alter transcripts of pro-IL-1/caspase 1 namely through NFκB modulation." (PMID 29654318, 2018). "In contrast to IL-1β expression, real-time PCR with the use of caspase-1 specific primers revealed a tendency towards reduced caspase-1 mRNA expression after stroke in MT-II-treated mice when compared to vehicle only treated mice after stroke, however without statistical significance." (PMID 26658636, 2015). "Inhibition of caspase-1 can attenuate NF-κB activity, not only prevents glial related pyroptosis, but also reduces the expression of pro-inflammatory factors, advances transformation of microglia to the anti-inflammatory type, thereby contributes to attenuation of inflammatory injury after stroke." (PMID 40289983, 2025). "Moreover, caspase-1 activation was completely blunted in ASC-deficient or AIM2-deficient, but not in cGAS-deficient, NLRP1-deficient or NLRP3-deficient, BMDMs in response to stimulation with serum from stroke mice or stimulation with DNA." (PMID 39112714, 2024). "Moreover, knockout of AIM2 or inhibition of caspase-1 could improve cognitive function and partly reverse brain volume in the hippocampus compared to those in stroke mice." (PMID 37332874, 2023). "However, the underlying interactions among caspase-1, BBB, and stroke still remain ill-defined." (PMID 35370546, 2022). "In addition, from a diagnostic point of view, our findings suggest that potentially ASC and caspase-1 may be used to diagnose stroke even beyond the acute phase." (PMID 30233311, 2018). "NLRP3 inflammasome activation following stroke is established in earlier studies to contribute to stroke injury through the pro-inflammatory cytokines (e.g. IL-1, IL-18) as well as the pleiotropic effects of cleaved caspase-1 in mediating pyroptosis and apoptosis." (PMID 29654318, 2018). "Further, GSDMD-N, the downstream target of cleaved-caspase-1, significantly increased at 6 h after stroke as well (** p < 0.01 vs. Sham group), while IPC inhibited stroke-induced upregulation of it (#p < 0.05 vs. pMCAO group)." (PMID 37371374, 2023). "Caspase-1 can be primed, triggered, and activated during acute stroke, and can participate in BBB dysfunction due to stroke-related oxidative stress, metabolic dysfunction, and mechanical stress." (PMID 35370546, 2022). "As specific caspase-1 inhibitors have been confirmed to alleviate BBB deterioration since 2010, targeting caspase-1 in stroke contributes to a promising end with a better functional outcome, milder cerebral edema, and lower occurrence of HT." (PMID 35370546, 2022). "In the present study, we demonstrated that THSWD attenuated mitochondrial DNA and nuclear DNA damage during stroke; reduced AIM2, NLRC4, and Caspase-1 inflammasomes; and inhibited IL-1β and IL-18 inflammatory factor release after IS." (PMID 36034843, 2022). "Post-stroke inflammasome activation, especially NLRP3, cleaved Caspase-1, cleaved Caspase-11, IL-1β, IL-18, and GSDMD, peaked at 3–5 days and declined at 7 days with the participation of multiple components in mice." (PMID 33967935, 2021). "Activation of TXNIP/NLRP3 inflammasome convert pro-caspase-1 into cleaved-caspase-1 and inhibits the TRX resulting oxidative stress in acute HG suture stroke model." (PMID 34681207, 2021). "Similar to our current study, recent studies have indicated that after stroke, miR-223 can downregulate NLRP3 to negatively regulate caspase-1 and IL-1β to suppress neuroinflammation." (PMID 34408803, 2021). "Meanwhile, compared to the stroke and stroke+PBS group, Ki20227 administration downregulated the expression of NLRP3, active caspase 1, and NF-κB protein in the ischemia penumbra of Ki20227 treatment group mice." (PMID 32908485, 2020).
Stroke (continued). "To understand the anti-stroke mechanism of QKL, we determined the protein expression levels of NLRP3, ASC, pro-caspase-1, cleaved-caspase-1, pro-IL-1β and cleaved-IL-1β in the brain tissue of rats." (PMID 31747940, 2019). "Protein levels of caspase-1, ASC and IL-18 were higher in the serum of stroke patients when compared to the control samples, whereas levels of IL-1β were not significantly different." (PMID 30233311, 2018). "Mechanistically, this age-dependent rescue may stem from exacerbated B-cell apoptosis in aged mice on day 7 post stroke, coupled with BM-MSC-mediated mitigation of caspase-1-dependent cell death in splenic marginal zone B cells, as previously reported." (PMID 41241718, 2025). "Similarly, pharmacological inhibition of the NLRP3/caspase-1 pathway reduces infarct volume and preserves BBB integrity across several preclinical stroke models." (PMID 41408503, 2025). "It was reported that NLRP3 inflammasome consisted of three protein subunits, NLRP3, ASC and caspase-1, the activity of NLRP3 inflammasome has been considered as one of the important factors in a variety of CNS diseases, such as Alzheimer’s disease and stroke." (PMID 38570868, 2024). "Therefore, investigation the prognostic value of markers in the NETs/AIM2 inflammasome axis, such as MPO-DNA, PAD4, HMGB1, C1q, AIM2, ASC, Caspase-1, IL-1β, IL-6 and IL-8, in LAA stroke patients is a meaningful endeavor." (PMID 39737165, 2024). "Neutrophils also undergo pyroptosis after a stroke; however, unlike macrophages, neutrophils are resistant to Caspase-1-induced pyroptosis." (PMID 37165005, 2023). "However, the effects NLRP3 inflammasome activation and pyroptosis after stroke were attenuated by IPC, which decreased the expression of NLRP3, ASC, cleaved caspase 1, and GSDMD-N and reduced the production of IL-1β and IL-18." (PMID 37371374, 2023). "Furthermore, caspase-1 was shown to induce apoptosis involving Bid (BH3-interacting domain) and mitochondrial-dependent activation of caspase-3 in stroke models." (PMID 31727879, 2019). "To determine which NLR sensor molecules were present in the clot of patients with stroke, we immunoblotted samples for NOD-like receptor protein-1 (NLRP1) and Absent in Melanoma-2 (AIM2); two receptors that form protein-protein interactions with caspase-1 and ASC to form an inflammasome complex." (PMID 33569001, 2020). "Hyperglycemia induces superimposed effects on caspase-1 in stroke, as specific NLRP3 inhibitor MCC950 showed stronger alleviation of BBB destructions in hyperglycemic stroke than stroke without hyperglycemia." (PMID 35370546, 2022).
melanoma (47 papers, 2012 to 2025). A malignant, usually aggressive tumor composed of atypical, neoplastic melanocytes. "Constitutive activation of the NLRP3 inflammasome causes late-stage human melanoma cells to spontaneously secrete IL-1β via Caspase 1 processing." (PMID 39201564, 2024). "Wild-type macrophages stimulated with ATP enhanced the metastatic potential of melanoma cells; however, NLRP3- or caspase-1-deficient macrophages lost the ability to promote metastasis of melanoma cells." (PMID 33534121, 2021). "Polymorphisms of NLRP3 are associated with the development of melanoma, and IL-1R-/- and caspase 1-/- mice rarely develop skin cancer after stimulation with chemical agents." (PMID 34064909, 2021). "Another study found that IL-1β and caspase-1-deficient mice were much less susceptible to melanoma liver metastases by an injected allograft, improving their overall survival." (PMID 24795727, 2014). "However, ASC protein expression is repressed in metastatic melanoma compared with primary melanoma, and inflammasome-associated caspase-1 and IL-1β are inhibited when the ASC gene is inhibited in primary and metastatic melanoma cells." (PMID 31242947, 2019). "Moreover, loss of NLRC4 or CASP1 promoted melanoma tumor progression." (PMID 34307322, 2021). "Dinaciclib 70 is a selective inhibitor of cyclin-dependent kinases (CDKs), CDK1,2,5,9, used to induce pyroptosis in melanoma through caspase-1/GSDME/Bax activation." (PMID 39316325, 2025). "It is interesting to note that B16-F10 tumors (Mock treated) grow less in Caspase-1/11-/-, Caspase-11-/- and IL-1R-/-, which confirms another study that showed the importance of IL-1β signaling in B16 melanoma tumor progression." (PMID 38835781, 2024). "-It is involved in the development of melanoma metastasis.-There is a positive correlation between caspase-1 levels and tumor mass, as well as resistance to treatment." (PMID 39329914, 2024). "On the contrary, the caspase-1 inhibitor, thalidomide, impedes tumor growth in melanoma by suppressing caspase-1 in MDSCs." (PMID 36932407, 2023). "LPS/ATP triggered the activation of NLRP3 inflammasomes, including caspase-1 activities, which enhanced the secretion of IL-18 and IL-1β, consequently resulting in an enhanced migratory ability of melanoma cells." (PMID 35682990, 2022). "In the GSDME immunofluorescent assays, pre-treatment of melanoma cells with caspase-1 inhibitor VX-765 or pan-caspase inhibitor Z-VAD-FMK suppressed the GSDME activation induced by the combined Hsp90 and PI3K inhibitors." (PMID 32156008, 2020). "Studies have also demonstrated a genetic association of polymorphisms in Nlrp1 gene in driving the tumorigenic process, which leads to an increase in the production of downstream mediators (i.e. CASP1 and IL-1β) in malignant melanoma." (PMID 30837326, 2019). "In line, many human tumors including advanced melanomas are characterized by high level IL-1β production due to both elevated pre IL-1β expression and enhanced Caspase-1 activity." (PMID 29983861, 2018). "Furthermore, vemurafenib 72 is a BRAF kinase inhibitor used to induce pyroptosis in melanoma through caspase-1/GSDME activation." (PMID 39316325, 2025). "Likewise, trametinib 78 is a dual kinase inhibitor used to induce the pyroptotic pathways in pancreatic cancer and melanoma through caspase-1/GSDMD activation." (PMID 39316325, 2025). "Studies have shown that caspase-1 plays a significant role in melanoma metastasis." (PMID 39329914, 2024). "Moreover, elevated levels of caspase-1 have been correlated with increased tumor mass and resistance to treatment in melanoma patients." (PMID 39329914, 2024). "In addition, active caspase 1, a genetic adjuvant in DNA vaccination against cancers, promoted pyroptosis to kill melanoma cells in mice." (PMID 38336727, 2024). "Interestingly, 3 of pyroptosis-associated genes including CASP1, CASP4 and PYCARD, can predict the effectiveness of anti-PD-1 immunotherapy for patients with melanoma." (PMID 36068291, 2022).